LINC01150 (long independently transcribed non-coding RNA 1150)
Synonyms: 2G7; TCONS_00019134
Gene: Long non-coding RNA gene on chromosome 11 (1,897,015 to 1,908,656, forward strand). Ensembl gene ENSG00000229671.
Diseases named in the same sentence as LINC01150 in open-access papers:
LINC01150 is named in the same sentence as 1 disease in open-access papers, as found by Europe PMC text mining. Sharing a sentence is not in itself a finding about the gene and the disease. The quoted sentences say what the papers report.
cancer (2 papers, 2023 to 2025). A tumor composed of atypical neoplastic, often pleomorphic cells that invade other tissues. "LINC01137, AC084859.1, and AC079949.2 were overexpressed whereas HSPC324, AC090617.5, and LINC01150 were significantly downregulated in cancer tissues compared with normal tissues of LUAD patients (p < 0.05)." (PMID 36305249, 2023).